CD4 (CD4 molecule)
Diseases named in the same sentence as CD4 in open-access papers (continued):
Sharing a sentence is not in itself a finding about the gene and the disease.
COVID-19 (continued). "Taken together, these results confirmed the existence of SARS-CoV-2-specific CD4+ T-cell and humoral responses in the majority of the individuals who had recovered from COVID-19 at 10 months post-infection." (PMID 34967260, 2022). "CD4+ T-cell reduction is common in adults with severe and moderate COVID-19 but was only seen in a small number of children in this study, consistent with the milder course of the disease." (PMID 36039499, 2022). "In conclusion, the correlation between CD4+ T cell responses and milder COVID-19 clearly tracks to early time points." (PMID 35806161, 2022). "In particular, through the use of HLA class I and II predicted peptides, “mega pools” circulating SARS-CoV-2-specific CD8+ and CD4+ T lymphocytes have respectively been found in 70% and 100% of COVID-19 convalescent individuals." (PMID 36694588, 2022). "Different CD4+ T cell subsets can play beneficial or detrimental roles in the progression of COVID-19." (PMID 36505489, 2022). "If instead we consider only the COVID-19 subjects with CD4+ T cell responses to the S protein, the magnitude of the response is not significantly different across disease severities." (PMID 35806161, 2022). "Most SARS-CoV-2 S-specific memory CD8+ and CD4+ T cells driven by COVID-19 vaccination recognize and respond to the S protein from the variants including Omicron." (PMID 36447262, 2022). "Here, we analyzed the changes in the proportions of CD4+ T-lymphocytes and the memory phenotype induced by vaccination against COVID-19 in participants naïve to COVID-19 and participants with a history of SARS-CoV-2 infection." (PMID 36298626, 2022). "We observed that the expression of ZBP1 was significantly increased in neutrophils, dendritic cells, macrophages, basophils, NK cells, CD4+ T cells and Treg cells from patients with COVID-19 compared with healthy controls." (PMID 35587515, 2022). "Our study also sought to explore the distribution and function of CD4+ T cells expressing cytotoxic molecules such as perforin, granzyme B, CD107a and granulysin in COVID-19 convalescent individuals." (PMID 35336918, 2022). "In this study, we first detected pairwise differentially expressed genes among the healthy, mild, and severe COVID-19 groups of patients based on the expression of CD4+ T cells and CD8+ T cells, respectively." (PMID 35601483, 2022). "Lymphocytopenia is a common outcome among COVID-19 patients, observed mainly as decreased counts of CD4 and CD8 T-cells." (PMID 35572964, 2022). "As for immunosuppressive properties, PD-L1 (CD274) is up-regulated and dysregulated in several types of immune cells of COVID-19 patients’ monocytes, neutrophils, gamma delta T cells, and CD4+ T cells." (PMID 36159873, 2022). "Meanwhile, higher numbers of CD4+ T-cell subtypes expressing GM-CSF and IL-6+ were observed in COVID-19 patients in the ICU with more severe pneumonia." (PMID 35615369, 2022). "Recent studies showed that profound depletion of CD4+ lymphocytes and NK cells is common in patients with severe COVID-19." (PMID 35736068, 2022). "Phenotypic analysis showed lower levels of PD-1 expression in CD4+ T cells of long-time COVID-19 clinically recovered patients than in those of healthy controls." (PMID 35615369, 2022). "We found that COVID-19 vaccination enhanced the mobilization of SARS-CoV-2-reactive TNFα-producing CD4+ and CD8+ T cells, and this enhancement was significant after the second dose of the vaccine was administered." (PMID 35669765, 2022). "In contrast, not only CD4+ and CD8+ T cells but also the CD8/CD4 ratios were remarkably decreased in severe COVID-19 cases." (PMID 36447262, 2022). "In this integrated study, we recorded the post-acute sequelae symptoms and tested the immune memories, including circulating antibodies, memory B cell, and memory CD4 or CD8 T cell responses of a cohort of 65 COVID-19 patients over 1-year after infection." (PMID 35240947, 2022).
COVID-19 (continued). "In this model we use a dynamic and multistable Boolean regulatory network to provide a mechanistic explanation of the lymphopenia and dysregulation of CD4+ T cell subsets in COVID-19 and provide therapeutic targets." (PMID 36678366, 2022). "Increased amounts of cytokines (i.e. IL-6) are associated with lymphopenia with decreasing CD4+ and CD8+ cell counts, and severe lung injury in patients with COVID-19 that lead to death." (PMID 35533178, 2022). "On the other hand, a reduction in the production of IFN-γ and granzyme A in CD4+ T lymphocytes in patients with COVID-19 was also reported in another study, indicating a functional change." (PMID 36359755, 2022). "We found an elevation of CD8+ TEMRA that lasted throughout the study, i.e., 6-7 months, which contrasted with the CD4+ TEMRA that remained unaltered by COVID-19." (PMID 36003367, 2022). "This indicates that the observed differences in the transcriptional profile of convalescent COVID-19 patients were mainly in monocytes and CD4+ T cells." (PMID 35464396, 2022). "COVID-19 patients have been shown to experience a reduced expression of CD73 on CD4+ and CD8+ T-cells, compared to healthy controls." (PMID 35746736, 2022). "Increased m6A regulator expression in COVID-19 patients results in the high expression of activated CD4 memory T cells." (PMID 36212830, 2022). "While SARS-CoV-2 spike-specific CD4+ T cell responses were detected in all COVID-19 convalescent patients, CD8+ T cell responses against the spike were detected in 70% of these patients." (PMID 36437407, 2022). "Nevertheless, patients with corona virus disease 2019 (COVID-19) not only show lower proportions of SARS-CoV-2-specific CD4+ or CD8+ T cells but also B cells and NK cells, with increasing disease severity." (PMID 36017493, 2022). "We determined the levels of SARS-CoV-2- and H1N1-specific CD4+ T cell responses in subjects recovered from COVID-19 one to 15 months ago by stimulating PBMCs with live SARS-CoV-2 or H1N1 influenza viruses." (PMID 36146622, 2022). "Conversely, the level of CD4+ T cells—regarded as a biomarker of protective immunity —is usually significantly reduced in adults with severe or critical COVID-19 compared to healthy controls." (PMID 35897696, 2022). "The CD4-RE epitope pool was tested in parallel with the S pool in the subset of 26 acute COVID-19 donors for which sufficient cells were available." (PMID 35806161, 2022). "The percentage of IL-22R1+ CD4+ T lymphocytes, both IL-22R+ and IL-22R1++, was mainly higher in severe patients compared to controls, suggesting a possible compensatory mechanism to impaired CD4+ T cell function in COVID-19 patients." (PMID 35422799, 2022). "For example, recent studies show that CD4 T cells and CXCR3-mediated recruitment of T cells into the gut potentially result in diarrhea associated with COVID-19, indicating the inflammatory immune response leads to subsequent gut dysfunction." (PMID 36297092, 2022). "We also observed an increased abundance of activated CD4+ T cells compared to the Naïve CD4+/CD8+ T cells in the COVID-19 patients." (PMID 36532041, 2022). "The percentage of CD3+CD4+IFN-gamma+ T cells displayed a significant 4-fold reduction in the severe COVID-19 group compared to participants developing a mild disease (P = 0.0034)." (PMID 35860236, 2022). "At the same time, recent studies in patients recovered from COVID-19, revealed the fundamental value of T lymphocytes (both CD4+ and CD8+ T cells) in conferring protection against SARS-CoV-2." (PMID 35746545, 2022). "In the early analysis of patients who died of COVID-19, the most notable findings were the significant decrease in circulating CD4+ and CD8+ T lymphocyte levels, and monocytes (monocytes and macrophages) were relatively dominant in the damaged myocardium." (PMID 35387441, 2022).
COVID-19 (continued). "Lymphocytopenia was found to be one of the most common features in laboratory tests of COVID-19 patients, and reduced CD4+ and CD8+ T cell counts were predictive of disease progression." (PMID 35619076, 2022). "In female COVID-19 patients, greater activation and differentiation of CD4+ and CD8+ T cells has been reported compared with males, although reduced CD8+ T cell responses were associated with disease severity in males only." (PMID 35418996, 2022). "In this study, we used the model to simulate the effect of various cytokine micro-environments characterized in mild, moderate, and severe COVID-19 and explore how these affect the differentiation and plasticity of CD4+ T cells." (PMID 36678366, 2022). "Several studies about the inactivated COVID-19 vaccines showed that the immunogenicity in PLWH with CD4 count < 200/μL was lower compared to HNC." (PMID 36325346, 2022). "In the context of ATI, the risk remains uncertain, but there is a hypothetical increased risk of severe COVID-19 outcomes for individuals with high HIV viral loads, and the associated immune activation and inflammation, or drop in CD4 T cell counts." (PMID 35382844, 2022). "A study of acute COVID-19 using combined measurement of CD4+ T cells, CD8+ T cells and neutralizing antibodies has suggested that co-ordination of these three arms of the adaptive response leads to lower disease severity." (PMID 35102311, 2022). "These COVID-19 vaccines can induce both SARS-CoV-2 specific CD4+ and CD8+ T-cell responses and neutralizing antibody production." (PMID 36583218, 2022). "In naïve individuals, this booster significantly increased the levels of spike-specific antibodies and B and CD4+ T cells, while in recovered COVID-19 individuals, the booster dose has minor effects, in line with what was observed for the second vaccine dose." (PMID 35833134, 2022). "Patients who had a poor COVID-19 outcome were less often on cART (75% vs. 93%, p = 0.0073) and had a lower median CD4+ cell count (403 [IQR: 172–582.5] vs. 568 [IQR: 348–861], p = 0.0099)." (PMID 35632714, 2022). "Studies on COVID-19 showed that CD4+ and CD8+ T lymphocyte ratios decrease with the severity of the disease." (PMID 36110850, 2022). "In our cohort, PLWH had quite low CD4+ levels at COVID-19 diagnosis (272 CD4+ cells/μL [IQR 127–468])." (PMID 35329872, 2022). "Our study is the first to our knowledge to describe a distinct CD4-expressing macrophage subset that becomes predominant specifically in the COVID-19 cases with ALI." (PMID 35446789, 2022). "The percentages of CD3+ and CD4+ T lymphocytes were also significantly lower in the COVID-19 patients." (PMID 35898494, 2022). "Timing is again crucial; indeed a study demonstrated that a fast induction of specific CD4+ T cells during the acute phase of the disease correlates well with milder COVID-19 and prompt viral clearance." (PMID 36289890, 2022). "Our data highlight that the correlation of CD4+ T cell responses with milder COVID-19 is most prominent in the first 2 weeks of infection and becomes less prominent at later time points." (PMID 35806161, 2022). "Multivariable analysis of the COVID-19 cases showed that higher CD4+ macrophage density and lung macrophage CD4 expression level both remained significant predictors of lower alveolar epithelial cell density even after adjustment for the presence of ALI." (PMID 35446789, 2022). "Immune suppression observed in COVID-19 patients was attributed to a decrease in CD4+ and CD8+ T cells." (PMID 36013183, 2022). "Compared with SARS-CoV-2– T cells, a fraction of SARS-CoV-2–specific CD4+ T cells expressed low/moderate levels of CCR7, which revealed the induction of distinct CD4+ T cell differentiation hierarchies after COVID-19 vaccination." (PMID 35230977, 2022). "Poor cross-recognition of SARS-CoV-2-specific CD4+ and CD8+ T cell responses between wt and beta variants in wave 1 and wave 2 COVID-19 participants." (PMID 35880744, 2022).
COVID-19 (continued). "Impaired bronchoalveolar macrophages, reduced CD4+ and CD8+ T cells, endothelial damage, destruction of pneumocytes and thrombosis associated with COVID-19 predisposes to secondary bacterial and opportunistic fungal infections." (PMID 35419223, 2022). "Our previous study demonstrated that early humoral immune response (Day 70) to this inactivated COVID-19 vaccine was delayed in PLWH who are stable on antiretroviral therapy (ART) with unsuppressed CD4 count than that in HNC." (PMID 36325346, 2022). "Overall, we found that our post-COVID-19 proteome signature was best replicated in diverse CD4+ T cell populations, as well as CD8+ T cells and monocytes." (PMID 36405747, 2022). "Overall, C-Vx seems to be an effective agent inducing the proliferation particularly of CD3+ and CD4+ T cells in healthy donors and patients with mild to moderate COVID-19." (PMID 36106521, 2022). "The CD4+ macrophages in COVID-19 also expressed several other markers of monocyte-derived alveolar macrophages, including the APOE transcript and genes encoding the complement component C1Q." (PMID 35446789, 2022). "If the CD4+ T-cell response is delayed, in some cases even for more than 22 days, then the outcome of COVID-19 will be more serious, even fatal." (PMID 36430430, 2022). "In this paper, we present a model to explain the behavior of T CD4+ cells during COVID-19 and to propose possible interventions to modulate these cells." (PMID 36678366, 2022). "For PD-1-positive T and B lymphocyte subsets, notable increases were observed between controls and patients with moderate or severe COVID-19 for CD4+PD-1+ T cells, CD8+PD-1+ T and CD19+PD-1+ B cells." (PMID 35741107, 2022). "Using flow cytometry, it was shown that T cell subsets, which play a major role in the orchestration of the whole adaptive immune response, such as IFNg+ and triple+CD4+, were significantly lower in COVID-19-naive older participants." (PMID 36140549, 2022). "Participants under 50 years of age showed significant increases in the percentage of CD4+ T cells in blood following COVID-19." (PMID 35719387, 2022). "Whereas uninfected lung tissue contains a predominant CD163+ macrophage population that is negative for the other lineage markers, we observed increased density of CD4+CD163+ macrophages in the COVID-19 cases with ALI." (PMID 35446789, 2022). "Although, some studies which evaluated heterologous prime-boost COVID-19 vaccine of different platforms have reported higher frequency of spike-specific CD4+, CD8+ T-cells, strong and high titers of neutralising antibodies against B1.1.7 and B.1.351 strains." (PMID 35519174, 2022). "Representative dot-plots exemplify the contrast of CD3+CD4+ T cells expressing IFN-gamma in whole blood samples exposed to polyclonal molecules from participants who experienced mild or severe COVID-19 throughout the follow-up." (PMID 35860236, 2022). "A study found that patients who died of COVID-19 had fewer IFN-γ-secreting CD4+ T cells than those with mild illness and rehabilitation." (PMID 35891267, 2022). "The decrease in CD4+ T cells among patients with severe COVID-19 has shown to be more pronounced and prolonged over time." (PMID 35453526, 2022). "In a study of T cells, a higher proportion of CD8+T cells than CD4+T cells was found in patients with mild COVID-19, suggesting a potential protective role for CD8+T cells in mild disease." (PMID 36420258, 2022). "Studies have shown that CD8+ T cells in patients with COVID-19 are usually observed within 7 days of symptom onset, with level peaking at 14 days, and are more activated than CD4+ T cells." (PMID 36189203, 2022). "COVID-19 patient-derived samples showed somewhat stronger CD4+ and CD8+ responses to peptides compared to vaccinees." (PMID 35529867, 2022). "Several severe cases of COVID-19 present a neutrophil increase and a decrease in CD4+ T cells leading to an immunosuppressive microenvironment." (PMID 36359334, 2022).
COVID-19 (continued). "EWAS analysis reveals that, though not genome-wide significant, there is a preponderance of hypermethylated sites and down-regulated methylation in convalescent COVID-19 patients, explicitly originating from monocytes and CD4+ T cells." (PMID 35464396, 2022). "Th1 and Th17 are often characterized by CXCR3 and CCR6, respectively, and CXCR3+ and CCR6+ SARS-CoV-2-specific CD4+ T cells were both detected during acute COVID-19." (PMID 35992306, 2022). "An increase in pro-inflammatory Th17 cells and lymphopenia associated with decreased CD4+ T cells, CD8+ T cells, and natural killer cells, and increased cytokine levels (IL-6, IL-10, and TNF-α) were observed in COVID-19 patients." (PMID 36353605, 2022). "Another study showed that the proportion of PD-1+ICOS+ and CD38+HLA-DR+ cells increased within the CXCR5+CD4+ Tfh pool in the circulation in all patients with COVID-19." (PMID 35632823, 2022). "Patients with COVID-19 have shown an unbalanced T cell homeostasis with reduction of multi-function CD4+T cells and higher degree of CD8+T cell exhaustion, leading to reduction in T cell subsets and an ineffective cellular immune response." (PMID 35601440, 2022). "In essence, when comparing the recovered severe COVID-19 patients to the unexposed participants, antigen-specific T-cell studies revealed a predominant role of CD4+ T cells over CD8+ T cells." (PMID 36248882, 2022). "There have been studies showing that some patients with severe COVID-19 have impaired CD4+ T cell function, which includes lowered IFN-γ production." (PMID 36034704, 2022). "Multiple studies have reported that the drastically reduced numbers of NK cells, CD4+ and CD8+ T cells in COVID-19 patients was associated with severity of the disease 17-19." (PMID 35919814, 2022). "A recent study in COVID-19 host genetics found that BATF2 controls the production of cytokines from CD4+ T-cells and macrophages in mice and participates in interferon signaling, highlighting a potential immunotherapeutic target to mitigate COVID-19." (PMID 35746678, 2022). "Analysis of blood transcript modules (BTMs) between patients with COVID-19 or influenza revealed upregulated BTMs in COVID-19 related to the cell cycle and adaptive immune response, primarily CD4+ T cells, B cells, plasma cells and immunoglobulins." (PMID 35663963, 2022). "Some studies have indicated that the administration of two doses of the BNT162b2 mRNA COVID-19 vaccine increases the expansion of antigen-specific CD4 + CD40L + T cells." (PMID 36298474, 2022). "In natural infection, long-lasting SARS-CoV-2-specific memory T cells observed in convalescent COVID-19 patients displayed a phenotype of central memory CD4+ T cells (CD4+CCR7+CD45RA-) or stem cell-like memory CD4+ T cells (CD4+CCR7+CD45RA+)." (PMID 35309363, 2022). "Overall, we observed that in donors with previous COVID-19, both S and M proteins were equally good targets for CD4 responses." (PMID 36139625, 2022). "A COVID-19-related impairment in CD4+ T cells promotes the excessive activation and possibly subsequent exhaustion of CD8+ T cells." (PMID 35891232, 2022). "Further, SARS-CoV-2 seems to trigger an innate functionality in a subset of T cells, namely highly activated CD16+ T cells, which occur mainly in severe COVID-19 in the CD4, CD8 and γδ T cell compartments." (PMID 35581387, 2022). "Single-cell analysis of T-cells from COVID-19 patients revealed that CD4+ T-cells were activated with high expression of regulatory responses and CD25 as well as suppression of FOXP3 expression in severe COVID-19." (PMID 35763685, 2022). "The proliferative CD4+ T-cell response was similar in vaccinated subjects and patients with pneumonia, but was lower in mild COVID-19 patients and persisted in both vaccinated subjects and post-COVID patients." (PMID 35744768, 2022). "Dysregulations of T cells including CD4+ and CD8+ T cells are reported in COVID-19 and are linked with the high risk of severity of this disease." (PMID 36290585, 2022).